SETD4 (SET domain containing 4)
Diseases named in the same sentence as SETD4 in open-access papers (continued):
Sharing a sentence is not in itself a finding about the gene and the disease.
cancer (9 papers, 2013 to 2025). A tumor composed of atypical neoplastic, often pleomorphic cells that invade other tissues. "Our pan‐cancer GSEA yielded significant insights into the association between SETD4 expression and critical signaling pathways in cancer." (PMID 39817582, 2025). "Herein, we thoroughly explored the gene expression profile and prognostic significance of SETD4, as well as its associations with the immune microenvironment and cancer‐related pathways in TCGA data sets." (PMID 39817582, 2025). "Although SETD4 has recently been implicated in cancer progression and drug resistance, the underlying mechanisms have yet to be unraveled, and a comprehensive pan‐cancer analysis is essential." (PMID 39817582, 2025). "Several early reports had implicated SETD4 expression in promoting growth and drug resistance of cancer cells." (PMID 35854936, 2022). "Furthermore, SETD4 expression was assessed in relation to cancer‐associated pathways, the immune microenvironment, immunotherapy markers, tumor stemness, and genomic instability." (PMID 39817582, 2025). "The correlation between SETD4 and cancer stemness as well as homologous recombination deficiency varied across tumor types, suggesting that SETD4 may play a multifaceted role in tumor resistance." (PMID 39817582, 2025). "Thus, the association between SETD4 expression and the outcome of cancer treatment would need to be assessed in a cancer type-specific manner." (PMID 35854936, 2022). "Interestingly, in two of these cases variants of genes involved in genome (POLQ) or chromatin (SETD4) stability were detected, so these findings also open new avenues for investigating cancer susceptibility." (PMID 28050010, 2017). "Additional correlation analysis revealed that SETD4 correlated negatively with the infiltration of different immune cell types (including B cells, macrophages, and NK cells) in most cancer types." (PMID 39817582, 2025). "Based on these findings, SETD4 can be recognized as a crucial player in the pathogenesis and progression of cancer." (PMID 39817582, 2025). "As a result, the HR of SETD4 was calculated for OS and PFS in various cancer types, revealing that SETD4 upregulation poses a risk for poor OS in ACC, KIRC, and PCPG and a risk for worse PFS in PRAD, ACC, LIHC, and UVM." (PMID 39817582, 2025). "As a result, we examined the correlation between SETD4 expression and HRD, revealing significant associations in a few cancer types." (PMID 39817582, 2025). "A comprehensive inquiry into the relationship between SETD4 and cancer‐related pathways is also needed." (PMID 39817582, 2025). "Within the TCGA cohort, SETD4 mRNA levels were analyzed in tumor and normal tissues to investigate the effect of SETD4 on various cancers." (PMID 39817582, 2025). "The role of SETD4 in various cancers was also elucidated through the construction of co‐expression and coregulatory networks, highlighting its significance as a driver gene in multiple tumor types, as well as the need for additional relevant investigations." (PMID 39817582, 2025). "Based on these findings, we delved deeper into the prognostic values of SETD4 methylation in various cancers." (PMID 39817582, 2025). "The link between SETD4 expression and HRD‐induced genomic instability markers [LOH, TAI, and LST] was further analyzed, revealing consistent patterns with HRD, thus implying a potential link between SETD4 and genomic instability in cancer." (PMID 39817582, 2025). "Herein, we found a strong relationship between SETD4 expression and immune‐related pathways in various cancers." (PMID 39817582, 2025). "Using data from the GDSC and CTRP [GDSC1, GDSC2] databases, a drug sensitivity analysis was further conducted to evaluate the influence of SETD4 on the responsiveness of malignant tumors to pharmacological interventions." (PMID 39817582, 2025).
cancer (continued). "Herein, we elucidated the influence of SETD4 on immune‐related pathways in various cancers, presenting it as a promising biomarker for immunotherapeutic interventions." (PMID 39817582, 2025). "According to the results, SETD4 was still upregulated in most of the cancers, such as BLCA, COAD, HNSC, and STAD, and downregulated in KICH and THCA." (PMID 39817582, 2025). "Another interesting finding was that SETD4 was positively correlated with the EMT pathway in ACC, KICH, UVM, and THYM, suggesting a potential role of SETD4 in cancer metastasis." (PMID 39817582, 2025). "Further analysis was carried out for cancers in which patients having higher SETD4 expression presented a poorer prognosis." (PMID 39817582, 2025). "According to the results, SETD4 expression correlated positively with various cell cycle–related pathways (such as the G2M checkpoint and mitotic spindle pathways) across different cancer types." (PMID 39817582, 2025). "Utilizing The Cancer Genome Atlas database, and other publicly accessible platforms, we comprehensively analyzed SETD4 gene expression, methylation patterns, and prognostic significance." (PMID 39817582, 2025). "Specifically, we discovered a correlation between SETD4 upregulation and the activation of cell cycle‐related pathways in various cancers, suggesting the potential involvement of SETD4 in cancer cell proliferation." (PMID 39817582, 2025). "We further conducted a detailed examination of the impact of SETD4 on the 10 prominent cancer‐related pathways using data from the TCPA cohort." (PMID 39817582, 2025). "More in-depth studies are much needed to explore the therapeutic potential of targeting SETD4 in cancer intervention." (PMID 35854936, 2022). "The present study provides the first characterization of a novel lysine methyltransferase, SETD4, which is related to cancer." (PMID 24738023, 2013). "We next evaluated the detailed cell cycle status of SETD4 knockdown cells and confirmed that the proportion of cancer cells in S phase was significantly decreased." (PMID 24738023, 2013). "Furthermore, we evaluated the prognostic influence of SETD4 on tumor development and recurrence across various cancer types by using K–M survival analysis." (PMID 39817582, 2025). "These discoveries emphasize the importance of SETD4 as a prognostic indicator in cancer." (PMID 39817582, 2025). "We then constructed a SETD4‐centric co‐expression and coregulatory network specific to each cancer type using the co‐expression patterns of SETD4 and its correlated genes, along with their regulatory mechanisms within cancer‐related pathways." (PMID 39817582, 2025). "Furthermore, the epigenetic regulation of SETD4 and its influence on cancer cell stemness should be explored further." (PMID 39817582, 2025). "Overall, SETD4 may function as an oncogene in specific cancer types, with its overexpression potentially contributing to disease progression." (PMID 39817582, 2025). "Herein, we demonstrated the oncogenic role of SETD4 in various TCGA cancer types." (PMID 39817582, 2025). "In addition, SETD4 negatively affects immune cell infiltration in most cancers, including B cells, CD8 T cells, and macrophages." (PMID 39817582, 2025). "Additionally, the effects of SETD4 on the EMT pathway showed opposite patterns across different cancers, with activation in HNSC, LIHC, THCA, and THYM and inhibition in DLBC, LGG, SARC, TGCT, and UCEC." (PMID 39817582, 2025). "Consistent with our previous study, we found that a large proportion of the surviving cells were SETD4-positive and Ki67-negative and exhibited high expression of cancer stem cell markers, including ALDH1 and CD133, supporting the notion that they were quiescent LCSCs." (PMID 37274024, 2023). "SETD4 is reported to epigenetically control breast quiescent cancer stem cells." (PMID 37926288, 2023). "We first characterized SETD4-positive cancer cells in NSCLC patient specimens." (PMID 37274024, 2023).
cancer (continued). "Oncogenic fusions of SETD4 have also been identified in cancer, albeit rare." (PMID 35854936, 2022). "However, others have observed SETD4 staining predominantly in the nucleus of quiescent mouse stem cells, quiescent cancer stems cells and numerous proliferative cancer cells." (PMID 35854936, 2022). "For SETD4 and DIS3L, where the ΔuAUG variants caused enhanced translation of the downstream CDS, ectopic overexpression of the related proteins has previously been linked to several types of human cancer and was associated with poor overall survival." (PMID 34072580, 2021). "Concomitantly, the percentage of cancer cells in G1 phase was increased, indicating that SETD4 could be a critical factor in the regulation of the G1-S transition in cancer cells." (PMID 24738023, 2013). "To determine the significance of SETD4 in human carcinogenesis, we examined whether SETD4 is involved in the growth regulation of cancer cells." (PMID 24738023, 2013). "Overall, SETD4 holds great potential for use as a novel therapeutic target for certain malignancies, and the synergistic manipulation of its related pathways along with immunotherapy or chemotherapy may be clinically valuable in cancer treatment." (PMID 39817582, 2025). "SETD4 holds great potential as a novel therapeutic target for certain malignancies, and the synergistic manipulation of its related pathways along with immunotherapy or chemotherapy may be clinically valuable in cancer treatment." (PMID 39817582, 2025). "Given SETD4's potential involvement in carcinogenesis, cancer advancement, and drug resistance, there is a pressing need to delve deeper into its significance in biological processes as well as its potential clinical relevance in cancer onset, progression, and treatment." (PMID 39817582, 2025). "According to the results, SETD4 correlated negatively with the major histocompatibility complex (MHC) and effector cells (ECs) in most cancer types and positively with suppressor cells (SCs) and immune checkpoints (CPs)." (PMID 39817582, 2025). "In a second study from the same laboratory, it was shown that exogenous expression of mammalian SETD4 enhanced the level of H4K20me3 in MCF-7 and HCC1937 cancer cells, and purified mammalian SETD4 produced H4K20me3 in vitro." (PMID 35854936, 2022).
tumor (3 papers, 2022 to 2025). "SETD4 overexpression was suggested to associate with estrogen receptor-positive breast cancer, albeit a limited number of cell lines and tumor tissues were analyzed." (PMID 35854936, 2022). "According to the promoter methylation status analysis conducted on tumor and normal samples, SETD4 was hypomethylated in both." (PMID 39817582, 2025). "A limited number of systematic studies have examined SETD4's role in the tumor microenvironment, pathogenesis, prognosis, and therapeutic response." (PMID 39817582, 2025). "Herein, we used mRNA expression and DNA methylation data to examine the relationship between SETD4 and tumor stemness indicators (specifically mRNAsi and mDNAsi)." (PMID 39817582, 2025). "Despite SETD4's propensity to induce increased tumor stemness and drug resistance, the availability of a greater variety of targeted drugs for chemotherapy is a promising development." (PMID 39817582, 2025). "Nonetheless, systematic investigations into the role of SETD4 in cell cycle regulation, tumor stemness, and related pathways are required to further elucidate its contribution to tumor resistance against immunotherapeutic and chemotherapeutic agents." (PMID 39817582, 2025). "We then identified the level of SETD4-positive cells in tumor samples obtained from 166 NSCLC patients." (PMID 37274024, 2023). "In summary, SETD4 confers chemoresistance, tumor progression, and a poor prognosis by regulating CSCs in NSCLC patients." (PMID 37274024, 2023). "We observed significant enlargement of tumor lesions after 2 cycles of chemotherapy in case 1 and case 2, both of which had high expression of SETD4." (PMID 37274024, 2023). "This is an extension of a previous study and validated that SETD4-positive qCSCs exert therapeutic resistance across different tumor types." (PMID 37274024, 2023). "Conversely, we observed tumor shrinkage in case 3 and case 4, both of which had low expression of SETD4." (PMID 37274024, 2023). "Then, we selected 21 chemoresistant patients and 21 chemosensitive patients and retrospectively analyzed the proportion of SETD4-positive qLCSCs in tumor tissue obtained before chemotherapy." (PMID 37274024, 2023). "The findings indicate a positive relationship between SETD4 expression and tumor purity, further confirming the potential correlation between high SETD4 expression and lower immune cell infiltration, which could explain immunotherapy failure." (PMID 39817582, 2025). "In summary, newly emerging evidence suggests that altered SETD4 activities may contribute to different aspects of tumorigenesis and mediate tumor response to therapy." (PMID 35854936, 2022). "However, it remains unclear whether SETD4 could be an indicator of quiescent CSCs in different tumor types, and it also needs to be further verified whether SETD4-positive quiescent CSCs are correlated with tumor progression and prognosis." (PMID 37274024, 2023). "However, it should be cautioned that the specific consequence of SETD4 alterations could be significantly influenced by the biological context of the specific tumor." (PMID 35854936, 2022). "In the present study, we confirmed the existence of a group of SETD4-positive cells, defined as qLCSCs, in tumor tissues from early-stage NSCLC patients and found that the proportion of SETD4-positive qLCSCs in advanced-stage patients was significantly higher than that in early-stage patients." (PMID 37274024, 2023). "The proportion of SETD4-positive qLCSCs in tumor tissues from advanced-stage (stages III and IV) patients (0.68 ± 0.13% and 0.78 ± 0.14%, respectively) was significantly higher than that in tumor tissues from early-stage (stages I and II) patients (0.12 ± 0.02% and 0.19 ± 0.04%, respectively)." (PMID 37274024, 2023).
cardiac diseases (1 paper, 2021). "Our findings suggest Setd4 and/or Setd4+ quiescent c-Kit+ cells may be also used as key targets in clinical treatment for wide range of cardiac diseases." (PMID 34079011, 2021).
hematological malignancies (1 paper, 2021). "The poorly characterized methyltransferase SETD4 was recently identified as a modulator of hematopoietic differentiation, suggesting that overexpression of SETD4 may also be important for the development of hematological malignancies." (PMID 34072580, 2021).
SETD4 also shares sentences with these, for which no sentence is quoted: cholangiocarcinoma (1 paper); colon adenocarcinoma (1); esophageal carcinoma (1); gestational choriocarcinoma (1); head and neck squamous cell carcinoma (1); hepatocellular carcinoma (1); infection (1); infertile (1); lung adenocarcinoma (1); lung squamous cell carcinoma (1); lymphoid neoplasm (1); pheochromocytoma (1); rectal cancer (1); rectum adenocarcinoma (1); rectum tumors (1); testicular germ cell tumor (1); thymic lymphoma (1); thyroid carcinoma (1); trisomy 21 (1); uterine corpus endometrial carcinoma (1); uveal melanoma (1).